HLA-B (major histocompatibility complex, class I, B)
Diseases named in the same sentence as HLA-B in open-access papers (continued):
Sharing a sentence is not in itself a finding about the gene and the disease.
autism (3 papers, 2014 to 2022). Persistent deficits in social interaction and communication and interaction as well as a markedly restricted repertoire of activity and interest as well as repetitive patterns of behavior. "Two of the HLA-B alleles were negatively linked to autism: HLA-B∗18:02 (P = 0.016, OR = 0.375) and HLA-B∗46:12 (P = 0.008, OR = 0.147)." (PMID 26819491, 2015). "In class I the HLA-A*01 (P = 0.03, OR 2.68), A*02 (P = 0.001, OR 3.02) and HLA-B*07 (P = 0.01, OR 3.27), were significantly associated with autism." (PMID 24672722, 2014). "In HLA class I HLA-A*01 (P = 0.03, OR 2.68), HLA-A*02 (P = 0.001, OR 3.02) and HLA-B*07 (P = 0.01, OR 3.27) alleles were found to be significantly associated with autism." (PMID 24672722, 2014). "However, the understanding of how HLA-B alleles have an impact on autism still needs more investigation." (PMID 26819491, 2015). "Moreover, we found that the HLA-B⁎18:02 (P = 0.016, OR = 0.375) and HLA-B⁎46:12 (P = 0.008, OR = 0.147) alleles were negatively associated with autism when compared to normal controls." (PMID 26819491, 2015). "This is the first report on HLA-B associated with Thai autism and may serve as a marker for genetic susceptibility to autism in Thai population." (PMID 26819491, 2015). "This is the first report on a foreseeable risk of association of HLA-B*07 allele with autism." (PMID 24672722, 2014). "In the present study the HLAB*07 is the allele that is significantly associated with autism." (PMID 24672722, 2014). "In conclusion despite a relatively small sample size, this research reports and for the first time a foreseeable risk association of HLA-B*07 allele and the closely linked haplotypes A*01 B*07 DRB1*0701 DQB1*0602 might serve as genetic markers for susceptibility to autism in Saudis." (PMID 24672722, 2014). "Thus, HLA-B*07 allele and the closely linked haplotype A*01 B*07 DRB1*0701 DQB1*0602 may serve as a marker for genetic susceptibility to autism in Saudis." (PMID 24672722, 2014).
autoimmune thyroid disease (3 papers, 2017 to 2023). Inflammatory disease of the thyroid gland due to autoimmune responses leading to lymphocytic infiltration of the gland. "Similarly, the HLA-B*35 allele is associated with autoimmune thyroiditis due to CTL dysfunction." (PMID 32760139, 2020). "The HLA-B*15-DRB1*04-DRB4* haplotype was associated with the co-occurrence of LS and thyroid autoimmunity." (PMID 28701998, 2017).
B cell lymphomas (3 papers, 2018 to 2023). "Mutational profiling using a custom panel of 168 genes associated with aggressive B-cell lymphomas confirmed mutations in ACTB, ARID1B, DUSP2, DTX1, HLA-B, PTEN, and TNFRSF14." (PMID 36975733, 2023). "We identified 666 mutations from 262 genes in baseline cfDNAs from 79 B-cell lymphoma patients, and found some genes were preferentially mutated in our cohort such as GNAQ, GNAS, H3F3A, DNMT3A, HLA-A, and HLA-B." (PMID 34926267, 2021).
bladder cancer (3 papers, 2023 to 2025). "Region-specific analysis reveals that PI3K-Akt signaling pathway regulated by HLA-A and HLA-B is involved in Chinese patients with bladder cancer compared to Americans." (PMID 40768543, 2025). "In conclusion, although our data should be confirmed in experimental models and clinical trials, they suggest that the study of the HLA-B −21M/T genotype could contribute to optimizing immunotherapy in patients with bladder cancer." (PMID 39857739, 2025).
celiac disease (3 papers, 2015 to 2018). An autoimmune genetic disorder with an unknown pattern of inheritance that primarily affects the digestive tract. "In addition, while the major genetic determinant in celiac disease, HLA-DQ2, is present on the AH8.1 haplotype, it can also be present on other haplotypes (e.g. HLA-B*18-DRB1*03) or be encoded in trans, meaning that the results are not directly transferable." (PMID 26207384, 2015).
cerebral malaria (3 papers, 2008 to 2014). A sequestration of Plasmodium falciparum in the brain, which can cause coma and/or seizures. "Beside drug hypersensitivity, other studies of HLA-B alleles, such as HLA-B*46:01, report a significant increase in severity of cerebral malaria compared with patients with mild CNS symptoms." (PMID 25657656, 2014). "This allele was not in significant LD with HLA-DRB1 and HLA-B alleles indicating that association with susceptibility to cerebral malaria was not because of LD with the HLA alleles." (PMID 18194515, 2008).
cerebrovascular disease (3 papers, 2021 to 2024). "A recent GWAS of white matter biomarkers in cerebrovascular disease has also revealed alterations in immune cell genes including human leukocyte antigen B (HLA‐B), major histocompatibility complex I (MHC I and HLA‐S), cell‐surface proteins involved in immune system regulation." (PMID 37909242, 2024).
chronic kidney disease (3 papers, 2017 to 2025). Impairment of the renal function secondary to chronic kidney damage persisting for three or more months. "The risk of developing allopurinol-induced severe cutaneous adverse drug reactions is 1.6%–2.0% for HLA-B*58:01 carriers, for patients with chronic renal insufficiency the risk is increased to 8%–18% to develop a SCAR." (PMID 37908589, 2023). "This study expands our knowledge of the distribution of MICA polymorphisms and linkage disequilibrium with HLA-B alleles, helping to elucidate possible associations with different diseases in patients with chronic kidney disease." (PMID 28419176, 2017).
Crohn disease (3 papers, 2012 to 2024). A gastrointestinal disorder characterized by chronic inflammation involving all layers of the intestinal wall, noncaseating granulomas affecting the intestinal wall and regional lymph nodes, and transmural fibrosis. "In a cohort of 2650 Crohn’s disease cases, HLA-B*08:01 and HLA-C*07:01 (which are in tight linkage disequilibrium with each other and with the class II genes of the haplotype) but not HLA-A*01:01 were significantly associated with good prognosis." (PMID 32238263, 2020).
depression (3 papers, 2019 to 2022). "HLA-B*08:01 was associated with modest protection for depression at the candidate threshold for testing in HLA genes in the meta-analysis (odds ratio = 0.98, 95% confidence interval = 0.97–0.99)." (PMID 31570195, 2020). "The allele with strongest evidence for association with depression was HLA-B*08:01, followed by HLA-DQB1*02:01 and HLA-DRB1*03:01." (PMID 31570195, 2020). "However, under a candidate threshold, correcting for SNPs within HLA genes, HLA-B*0801 had significant evidence for association with depression status." (PMID 31570195, 2020). "Unlike the associations of HLA-DPB1 with ASD and ID, the gene-based tests for HLA-B with ADHD or depression are not significant." (PMID 30976114, 2019).
endometriosis (3 papers, 2015 to 2020). The growth of functional endometrial tissue in anatomic sites outside the uterine body. "A literature search identified similar reports from China, which showed an association between endometriosis and the HLA-B*46, HLA-DRB1*15, and HLA-DQA1*0401 alleles." (PMID 32184413, 2020). "We asked whether polymorphisms in KIR, HLA-C, and HLA-B genes are risk factors for endometriosis." (PMID 25724317, 2015).
ependymoma (3 papers, 2023 to 2025). A WHO grade II, slow growing tumor of children and young adults, usually located intraventricularly. "For HLA-B, frequencies ranged from 0% in ependymoma to 31% (5 out of 16) in aHGG models, while the homozygosity frequencies of HLA-C ranged from 11% (2 out of 19) in neuroendocrine to 36% (12 out of 36) in bone and soft tissue sarcoma models." (PMID 41312385, 2025).
glaucoma (3 papers, 2022 to 2023). Increased pressure in the eyeball due to obstruction of the outflow of aqueous humor. "The gene HLA-B is highly associated with glaucoma in FinnGen (P = 8.0 × 10−9)." (PMID 36450729, 2022). "For example, CDCA8, HLA-B, RHOC, PPM1J, RPL10A, and TEAD3 are associated with glaucoma (P < 1 × 10−6)." (PMID 36450729, 2022). "Methazolamide, a carbonic anhydrase inhibitor used as an intraocular pressure‐lowering drug to treat glaucoma, was found to be associated with SJS/TEN in individuals with the HLA‐B*59:01 allele in Northeast Asia, including Korea, Japan, and China." (PMID 35070271, 2022). "In addition, a recent study using whole-exome sequencing identified rare variants and genes associated with IOP and glaucoma, including BOD1L1, ACAD10, and HLA-B, demonstrating the power of including and aggregating rare variants." (PMID 36980914, 2023).
IgA nephropathy (3 papers, 2012 to 2020). "HLA-B*4001 has also been shown to be associated with IgA nephropathy (OR = 1.34, P = 5.64 × 10−7), a known though uncommon association of AS." (PMID 32272966, 2020). "Another interesting issue is HLA-B*40, with a frequency of 16.26% in ESRD patients, which is identified as a susceptible allele for IgA nephropathy in Han Chinese through a genome-wide association study." (PMID 24603486, 2014).
Immunodeficiency (3 papers, 2018 to 2024). Failure of the immune system to protect the body adequately from infection, due to the absence or insufficiency of some component process or substance. "With the collection of HLA genotype samples, we promoted HLA-B*15:02 that has promising a risk factor for ceftazidime treatment in immunodeficiency patients." (PMID 39188942, 2024). "Moreover, the prevalence of RIT HLA-B molecules might be a reason that there is only mild immunodeficiency in TAP deficient humans, and RIT-HLA-I may be the dominant antigen presenting alleles in these patients." (PMID 29995954, 2018).
lipodystrophy (3 papers, 2013 to 2014). A congenital or acquired disorder characterized by abnormal loss or redistribution of the adipose tissue in the body. "In Asia, where the frequency of B*57:01 was low, associations between HLA-B*40:01 and lipodystrophy, and HLA-B*35:05 and rash were reported in small case-control studies." (PMID 25361850, 2014). "Moreover, HLA-B*40:01 is associated with lipodystrophy in Thai HIV-1-positive patients who received antiretroviral therapy containg stavudine." (PMID 25657656, 2014). "HLA-B*35:05 and female gender were strong predictors of regimen modification due to rash and lipodystrophy, respectively." (PMID 25361850, 2014).
lung adenocarcinoma (3 papers, 2017 to 2024). A carcinoma that arises from the lung and is characterized by the presence of malignant glandular epithelial cells. "We therefore investigated tumors with six distinct HLA alleles and loss of one HLA haplotype (HLA-A, HLA-B, and HLA-C) in at least one tumor region (n = 20; 9 lung adenocarcinomas and 11 lung squamous cell carcinoma)." (PMID 29107330, 2017). "A particular study revealed that MHC-I molecules, encompassing HLA-B and HLA-C, exhibited reduced expression in lung adenocarcinoma patients who were non-smokers compared to those who smoked." (PMID 38672772, 2024).
lymphoma (3 papers, 2016 to 2022). A malignant (clonal) proliferation of B- lymphocytes or T- lymphocytes which involves the lymph nodes, bone marrow and/or extranodal sites. "As HLA‐A*01, HLA‐A*03 and HLA‐B*37 have each been associated with differential susceptibility to EBV+ lymphomas 15, 16, 17, 53, we aimed to increase the number of defined EBV latency antigen‐derived epitopes restricted by these HLA class I molecules." (PMID 26422112, 2016).
megacolon (3 papers, 2012 to 2019). "The frequency of the HLA-B*14:02 allele was significantly lower in the ECG alteration and/or megacolon patients compared with those of indeterminate symptoms." (PMID 22448298, 2012). "The frequencies of HLA-DRB1*01 and HLA-B*14:02 were significantly lower in patients suffering from megacolon as well as in those with ECG alteration and/or megacolon compared with a group of patients with indeterminate symptoms." (PMID 22448298, 2012). "HLA-non classical class I, MICA*011, which was closely linked to HLA-B*14 and DRB1*01 might also be functional as MICA is known to stimulate gamma-delta T-cells in the gut mucosa; a phenomenon that could relate to megacolon." (PMID 22448298, 2012). "The association of MICA*011 and HLA-B*14 and DRB1*01 could relate to megacolon." (PMID 31126327, 2019). "In Bolivia, the frequencies of HLA-DRB1*01 and HLA-B*14:02 were significantly lower in patients suffering from megacolon, as well as in those with ECG alteration and/or megacolon, compared with a group of IND patients." (PMID 24069594, 2013).
myasthenia gravis (3 papers, 2021 to 2025). Myasthenia gravis (MG) is a rare, clinically heterogeneous, autoimmune disorder of the neuromuscular junction characterized by fatigable weakness of voluntary muscles. "The HLA-B*08:01 is involved in myasthenia gravis, while the HLA-A*24 and HLA-B*51 are associated with Behçet disease (BD)." (PMID 34447375, 2021).
nasopharyngeal carcinoma (3 papers, 2010 to 2024). A carcinoma arising from the nasopharyngeal epithelium. "However, others have documented the risk association of HLA-B*18 in Malay patients with nasopharyngeal carcinoma." (PMID 20927388, 2010).
neuroblastoma (3 papers, 2023 to 2025). Neuroblastoma (NB) is the most common solid, extracranial childhood tumor. "By contrast, neuroblastoma had low levels (HLA-A 6.5; HLA-B 1.0; HLA-C 3.4)." (PMID 41312385, 2025). "In contrast, no HLA-B and -C allele was detected from all three neuroblastoma PDXs with available RNA-Seq and only one HLA-A allele was detected in two of them, suggesting low transcript levels." (PMID 38318504, 2023). "Notably, HLA-B, TAP1 and TAP2 transcript levels were lower than the minimum values of control normal tissues (brain and testis) in ~80% of PDXs (32 out of 44), and B2M levels were also low in neuroblastoma, nephroblastoma, and all but one rhabdomyosarcoma tumors." (PMID 38318504, 2023).
osteosarcoma (3 papers, 2009 to 2023). A usually aggressive malignant bone-forming mesenchymal neoplasm, predominantly affecting adolescents and young adults. "We previously identified papillomavirus-binding factor (PBF) as a novel osteosarcoma antigen, using an osteosarcoma cell line and an autologous CTL (cytotoxic T lymphocyte) clone restricted by HLA-B*5502." (PMID 19523231, 2009). "Furthermore, three out of four Ewing sarcoma, two osteosarcoma, and single eRMS, aRMS, and HGG PDXs with high HLA class I IHC score showed low or negligible HLA-B transcript levels." (PMID 38318504, 2023). "Tumour samples from multiple stages of the disease (pretreatment biopsies, surgical resections of primary osteosarcomas, relapses and metastases) were collected and stained for HLA-A (HCA2), HLA-B/C (HC10), β2-microglobulin and PD-L1 using immunohistochemistry on whole sections." (PMID 27853827, 2017).
parasite infection (3 papers, 2008 to 2025). "The association of HLA-C*06:02 and HLA-B*53:01 with a higher risk of parasitemia could reflect greater KIR-mediated inhibition leading to dampened cellular immunity at pre-erythrocytic stages or an attenuated clearance of parasites via antibody dependent cellular cytotoxicity." (PMID 33815410, 2021). "Instead, we found that HLA-B*53:01-positive individuals had a higher odds of parasitemia, but trended toward a lower probability of symptoms when parasitemic." (PMID 33815410, 2021).
penicillin allergy (3 papers, 2020 to 2025). "For instance, HLA‐B*57:01 has been associated with flucloxacillin‐induced liver injury, while HLA‐B*55:01 was recently reported as associated with self‐reported penicillin allergy." (PMID 40906332, 2025). "We present robust evidence for the role of an allele of the major histocompatibility complex (MHC) I gene HLA-B in the occurrence of penicillin allergy." (PMID 32888428, 2020). "The results of the analysis showed that carriers of the HLA-B*55:01 allele have a 33% higher relative risk of penicillin allergy than the rest of the population, which could point to a lymphocyte-mediated predisposition leading to a delayed penicillin reaction." (PMID 34680808, 2021). "Here we detect a robust association between self-reported penicillin allergy and an allele of the MHC class I gene HLA-B." (PMID 32888428, 2020).
pulmonary fibrosis (3 papers, 2015 to 2022). Chronic progressive interstitial lung disorder characterized by the replacement of the lung tissue by connective tissue, leading to progressive dyspnea, respiratory failure, or right heart failure. "HLA-B*62 and HLA-Cw*0602 has association with pulmonary fibrosis, while HLA-B*13 and HLA-B*65 with PAH." (PMID 26106387, 2015).
sarcoma (3 papers, 2021 to 2023). A usually aggressive malignant neoplasm of the soft tissue or bone. "In our STS population, deletion of the HLA-B region was frequent (10% of cases) mostly in stage III sarcomas." (PMID 35884474, 2022). "We now established that sarcoma select rare alleles of HLA-I loci and/or delete HLA-B locus and strongly down-regulate HLA-I mRNAs compared to normal tissues, consistent with similar findings reported for other cancer types." (PMID 35884474, 2022). "Importantly, 14 genes involved in the interferon gamma response were upregulated including HLA-B, HLA-C, PD-L1, IL2RB and TNFAIP6, suggesting the reprogramming of the immune microenvironment of sarcoma cells on chidamide inhibition." (PMID 33637599, 2021).
spondylitis (3 papers, 2015 to 2025). The inflammation of a vertebra. "HLA-B*27 cannot be used as a predictive marker in an asymptomatic subject, for two reasons mentioned by rheumatologists: the predictive value of the marker is low in this case; there is no way of prevention in the event of increased risk of spondylitis." (PMID 26528326, 2015).
Stroke (3 papers, 2019 to 2023). Sudden impairment of blood flow to a part of the brain due to occlusion or rupture of an artery to the brain. "HLA-A*24:02-*24:02 (8.6% vs. 2.7%, P value = 0.014), and HLA-B*46:01-*46:01 (0% vs. 5.3%, P value = 0.046) were significantly associated with stroke." (PMID 35321340, 2022). "With regard to HLA alleles, subjects without ischemic stroke showed in comparison with stroke subjects a significantly higher frequency of HLA-B-Bw4I alleles (65.1% vs 8.6%; p < 0.0001)." (PMID 30995924, 2019). "Our study showed that subjects with acute ischemic stroke in comparison with subjects without stroke were more likely to have a higher frequency of 2DL3, 2DL4, 2DL5B, 2DS2, 2DS4, and 3DP1 KIR genes and a significantly lower frequency of HLA-B-Bw4I allele." (PMID 30995924, 2019). "Subjects with acute ischemic stroke and subjects without stroke were genotyped for the presence of KIR genes and of the three major KIR ligand groups, HLA-C1, HLA-C2, and HLA-Bw4, both HLA-B and HLA-A loci." (PMID 30995924, 2019).
subacute thyroiditis (3 papers, 2021 to 2025). Self-limited inflammation of the thyroid gland characterized by the presence of multinucleated giant cells. "The HLA-B*18:01 allele is associated with an inflammatory thyroid disease known as subacute thyroiditis (SAT)." (PMID 34447375, 2021). "Interestingly, a strong association between HLA-C*04:01 and subacute thyroiditis (SAT) has been demonstrated in Caucasians, in addition to the previously known correlation between SAT and HLA-B*35." (PMID 39768617, 2024).
systemic sclerosis (3 papers, 2015 to 2024). A chronic disorder, possibly autoimmune, marked by excessive production of collagen which results in hardening and thickening of body tissues. "HLA-B*35 is associated with a high risk of developing PAH in systemic sclerosis by influencing the production of endothelin-1 (ET-1) and decreasing endothelial nitric oxide synthase (eNOS)." (PMID 26106387, 2015). "al. summarized a comprehensive correlation of the most significant associations within HLA-DRB1*04:04 and HLA-B*37, emphasizing that the alleles associated with morphea were different from those associated with systemic sclerosis (SSc), indicating that morphea is immunogenetically distinct from SSc." (PMID 39685593, 2024).